MSH6 (mutS homolog 6)
Diseases named in the same sentence as MSH6 in open-access papers (continued):
Sharing a sentence is not in itself a finding about the gene and the disease.
cancer (continued). "To address this, we performed pan-cancer analysis of MSH6 gene across 33 different cancer types, based on the data of TCGA, CPTAC, and GEO databases, as well as the molecular characteristics of gene expression, genetic alteration, or protein phosphorylation." (PMID 34941572, 2021). "MSH6 expression was also observed to be correlated with cancer-associated fibroblasts and CD8+ T-cells infiltration levels in various cancer types, e." (PMID 34941572, 2021). "Subsequently, we applied TCGA and GEO datasets to find the correlation between MSH6 expression and the prognosis of different cancer patients." (PMID 34941572, 2021). "Then, the potential relationship between genetic alteration of MSH6 and the clinical survival prognosis of patients with different types of cancer were also further analyzed." (PMID 34941572, 2021). "Altogether, our first pan-cancer analysis of MSH6 showed that MSH6 is expressed in most cancers, and the MSH6 expression is significantly correlated to the clinical prognosis of cancer patients, protein phosphorylation, and immune cell infiltration." (PMID 34941572, 2021). "We utilized the TIMER2 tool firstly to analyze MSH6’s expression status in the TCGA project’s different cancer types." (PMID 34941572, 2021). "In cancer, according to the expression level of MSH6, we divided cancer cases into two groups of MSH6 high-expression and MSH6 low-expression." (PMID 34941572, 2021). "The global importance of such rare variants in tumorigenesis has been addressed by pan-cancer analysis, revealing significant enrichments for protein truncating variants in genes such as ATM, BRCA1/2, BRIP1, and MSH6." (PMID 33809641, 2021). "The genetic alteration status and prognostic value of MSH6 across multiple cancer types and the relationship with immune cell infiltration were also investigated." (PMID 34941572, 2021).
cancer (continued). "A small, but unique group of 16 non-FAP mesenteric desmoid was found to harbor genetic alterations in cancer associated genes other than APC, including CHEK2, BLM, ERCC5, MSH6, and PALB2." (PMID 34359575, 2021). "On account of the available datasets of the cancer genome atlas (TCGA) and Gene expression omnibus (GEO), a comprehensive analysis of the potential carcinogenic effects of the MSH6 gene was conducted in 33 human cancers." (PMID 34941572, 2021). "Previous studies have shown that abnormal expression of the MSH6 gene and its transcription characteristics have been detected in many cancer types." (PMID 34941572, 2021). "Taken together, our research provided a new understanding of the potential effect of MSH6 in the pathogenesis or in clinical prognosis of various different cancers." (PMID 34941572, 2021). "The sisters in generation IV of Family 2 demonstrate a Mendelian inheritance pattern of the two familial cancer predisposition mutations in MSH6 and BAP1 (MSH6: Ex3_9del, pathogenic; BAP1: c.38-1G > A, likely pathogenic)." (PMID 33541411, 2021). "The contribution of the genetic variants, other than MSH6 and MUTYH, to cancer risk cannot be completely excluded." (PMID 32615015, 2020). "We found MSH6 expression to be correlated with elevated temozolomide sensitivity in cancer cell lines (Spearman’s rho = 0.165, p = 5.01E−7)." (PMID 32066500, 2020). "Digenic inheritance of monoallelic MSH6 variants of uncertain significance and MUTYH variants has been suggested to predispose to Lynch syndrome‐associated cancers; however, cosegregation with disease in the familial setting has not yet been established." (PMID 32615015, 2020). "Prognostic variants were identified in or near MSH6, POLQ, ARID5B, and IDH2, which are previously reported cancer driver genes." (PMID 32066500, 2020). "Here we demonstrate the coinheritance of monoallelic variants in MSH6 and MUTYH consistent with cosegregation with CRC, further supporting a role for digenic inheritance in cancer predisposition." (PMID 32615015, 2020). "In our series, 30.3% of MSH6 mutation carriers developed at least one CRC, and metachronous cancers were diagnosed in 0% of the individuals in the ES group vs. 16.7% in the SS group." (PMID 33218006, 2020).
cancer (continued). "The variants in cancer driver genes, MSH6, POLQ, ARID5B, and IDH2, warrant further study to determine the mechanism by which these variant affect cancer progression." (PMID 32066500, 2020). "Here, we demonstrate the coinheritance of MSH6 and MUTYH variants consistent with the cosegregation with cancer, further supporting a role for digenic inheritance in CRC predisposition." (PMID 32615015, 2020). "Digenic inheritance of monoallelic MSH6 and MUTYH variants has been suggested to predispose to Lynch syndrome‐associated cancers; however, cosegregation of both variants within CRC families has not yet been demonstrated." (PMID 32615015, 2020). "Using this threshold, both known somatic mismatch repair mutant (MLH1 and MSH6) cancers were MSI-H, with 55% and 67% of sites being unstable, respectively." (PMID 32306292, 2020). "MSI analysis by PCR revealed MSI-high in three cancers and MSS in the cancer with isolated MSH6 loss." (PMID 32108923, 2020). "The most frequently studied SNP of MSH6 is rs1042821 (c.116G>A; Gly39Ala), which was found to have controversial effects in cancer patients." (PMID 32756484, 2020). "Here, we demonstrate, for the first time, the coinheritance of monoallelic variants in MSH6 and MUTYH consistent with the cosegregation with CRC, further supporting a role for digenic inheritance in cancer predisposition." (PMID 32615015, 2020). "Amsterdam-II or Bethesda criteria used to identify MLH1/MHS2/MSH6 carriers in clinical practice miss 55–70% or 12–30% (respectively) of these MLH1/MHS2/MSH6 carriers even amongst those with cancer." (PMID 30400647, 2018).
cancer (continued). "Among 10 candidates tested only MSH6, a DNA mismatch repair enzyme, and DEK, a chromatin- and RNA-associated protein mutated or overexpressed in certain cancers, showed reliable immunostaining results." (PMID 22824167, 2012). "Even if germline mutation analysis of MSH6 is negative, the proband and his family members will still require strict cancer surveillance." (PMID 40469174, 2025).
cancer (continued). "We presumed MSH6 germline pathogenic variant was unlikely to be a direct driver of this cancer and was discovered incidentally." (PMID 40335734, 2025). "Conversely, LSVH with germline PVs in the MSH6 gene have an increased risk of endometrial cancer and a slightly higher risk of colorectal cancer (CRC), whereas LSVH with germline PVs in the PMS2 gene have a lower risk of developing any cancer." (PMID 39767815, 2024). "The genes FAN1, MSH6, and FANCI were among those with the highest number of VUS, complicating clinical decision-making due to the uncertain impact of these variants on hereditary cancer risk." (PMID 39710803, 2024). "They found that among 33 cancer types, UCEC had the most changes in the DNA damage repair gene somatic alterations, among which the incidence of MMR pathway-related gene mutations, especially MSH6, ranks second at 41%." (PMID 38390329, 2024). "In contrast, expression of MSH6 was lost from some carcinoma nuclei." (PMID 38243056, 2024). "Aberrant expression and transcriptional features of the MSH6 have been observed in cancer cells." (PMID 38139447, 2023). "Additionally, people with variants in low-penetrance genes, such as MSH6 and PMS2, have a lower risk of developing a cancer associated with LS, leading to families with unaffected generations and showing fewer clear patterns." (PMID 37864171, 2023). "MSH6 and POLQ may have slightly different potential cancer-associated trends in women and men, respectively." (PMID 36896836, 2023). "APC (P), BRCA2 (P), BUB1B (LP), ENG (LP) and MSH6 (P) were identified in patients with cancer." (PMID 36896836, 2023). "Onset of CRC is later for MSH6, with few or no cancers detected before 30–35 years of age, and the risk of CRC in PMS2 PV carriers before 50 years of age is negligible if undergoing active colonoscopy surveillance." (PMID 37165697, 2023).